HCP5 (HLA complex P5)
Diseases named in the same sentence as HCP5 in open-access papers (continued):
Sharing a sentence is not in itself a finding about the gene and the disease.
lung adenocarcinoma (14 papers, 2018 to 2022). A carcinoma that arises from the lung and is characterized by the presence of malignant glandular epithelial cells. "SMAD3-responsive HCP5 contributes to lung adenocarcinoma metastasis by targeting miR-203/SNAI signaling." (PMID 35602292, 2022). "For example, HCP5 is aberrantly expressed in several different cancers and correlates with poor prognosis in patients with lung adenocarcinoma." (PMID 36338651, 2022). "Several studies have demonstrated that HCP5 expression is enhanced in tumor tissues, including lung adenocarcinoma, anaplastic thyroid cancer, and colorectal cancer." (PMID 33439936, 2021). "Specifically, lncRNA HCP5 was found to be upregulated in lung adenocarcinoma (LUAD), resulting in increases of Snail and Slug to promote EMT progression by adsorbing miR-203." (PMID 31941509, 2020). "Research has shown that HCP5 promoted lung adenocarcinoma metastasis via the miR-203/SNAI axis and tumor growth and upregulated the expression of PD-L1/CD274 via a competing endogenous RNA mechanism of sponging miR-150–5p, and these were also consistent with our findings." (PMID 36147489, 2022). "lncRNA HCP5 induces the development of lung adenocarcinoma cells by targeting miR-203." (PMID 35602292, 2022). "In addition, HCP5 is overexpressed in tumor tissues of patients with lung adenocarcinoma, and it is positively correlated with poor prognosis specifically in patients who are smokers with EGFR and KRAS mutations." (PMID 31137555, 2019). "Furthermore, HCP5 over-expression can indicate a poor prognosis for lung adenocarcinoma patients." (PMID 32054031, 2020). "Similarly, HCP5 was also down-expressed in patients with lung adenocarcinoma." (PMID 30364292, 2018).
ovarian carcinoma (14 papers, 2013 to 2024). A malignant neoplasm originating from the surface ovarian epithelium. "During exploring the effect of lncRNAs on survival, HCP5 was associated with a good prognosis in lung cancer, breast cancer, and ovarian cancer." (PMID 35399723, 2022). "A total of 19 lncRNAs significantly related to prognosis of ovarian cancer were obtained using univariate Cox regression analysis, and the 5 prognostic signature lncRNAs GAS5, HCP5, PART1, SNHG11, and SNHG5 were used to establish a risk assessment system." (PMID 31182053, 2019). "Recent studies demonstrated that HCP5 (human leukocyte antigen (HLA) complex 5) is a target gene of hMOF, and marked down-regulation of hMOF and HCP5, and loss of H4K16 acetylation were observed in ovarian epithelial cancer tissues." (PMID 30064416, 2018). "In the present study, the expression of hMOF was frequently downregulated in the clinical ovarian cancer tissues and, more notably, HCP5 was presented in gene expression profiles as a hMOF-downregulated gene." (PMID 24137335, 2013). "It was first observed that HCP5 was significantly downregulated in ovarian cancer." (PMID 35810383, 2022). "LncRNA HCP5 is frequently downregulated in human ovarian cancer, suggesting that HCP5 may be involved in the pathogenesis of the disease." (PMID 31739287, 2019). "hMOF and its regulated gene, HCP5, are frequently downregulated in human ovarian cancer, suggesting that hMOF may be involved in the pathogenesis of the disease." (PMID 24137335, 2013). "Furthermore, the hMOF-regulated gene, HCP5, was also found to be downregulated in ovarian cancer tissues." (PMID 24137335, 2013). "Together, this suggests that HCP5, as a hMOF-target gene, may also be downregulated in ovarian cancer." (PMID 24137335, 2013). "Therefore, hMOF may have a role in modulation of tumor antigen-specific immune responses in ovarian cancer through modulating the expression of its target gene HCP5." (PMID 30064416, 2018). "In addition, HCP5 was significantly down-regulated in patients with ovarian cancer." (PMID 30364292, 2018). "By searching related literature and databases, about 30% lncRNAs have been verified to play roles in the regulation of proliferation, invasion, and migration of ovarian cancer cells, including ZFAS1, SNHG1, GAS5, EMX20S, GIHCG, TP53TG1, EPB41L4A-AS1, SNHG8, SNHG6, and HCP5." (PMID 33519912, 2020). "Furthermore, the mRNA expression levels of the hMOF-regulated non-protein coding human leukocyte antigen (HLA) complex P5 (HCP5) were examined in ovarian cancer tissues." (PMID 24137335, 2013).
breast carcinoma (13 papers, 2019 to 2024). "High levels of the HCP5-132aa protein were associated with a poor survival rate in breast cancer patients." (PMID 36980766, 2023). "Kaplan–Meier survival analyses revealed that patients with higher HCP5-132aa levels had a higher risk of breast cancer-related death compared to patients with lower HCP5-132aa expression levels (p < 0.0001, log-rank test)." (PMID 36980766, 2023). "Furthermore, increased levels of HCP5-132aa were positively associated with more advanced clinical stages of breast cancer (p = 0.002)." (PMID 36980766, 2023). "We also evaluated the expression of the HCP5-encoded products in a breast cancer tissue microarray." (PMID 36980766, 2023). "For example, in breast cancer, the LINC00908-encoded polypeptide ASRPS (a small regulatory peptide of STAT3), the lncRNA MAGI2-AS3-encoded polypeptide, and the lncRNA HCP5-encoded peptide have been proven to have functional roles in breast cancer pathogenesis." (PMID 39346726, 2024). "To investigate the role of the HCP5-132aa in breast cancer patients, we analyzed protein levels in tissue microarray analysis of 140 breast cancer tissues and 39 matched precancerous tissues using IHC assay." (PMID 36980766, 2023). "A lower histocompatibility leukocyte antigen complex P5 (HCP5) expression level was ascertained in cisplatin-resistant breast cancer cells, while overexpressed HCP5 weakened cisplatin resistance in vivo and in vitro by upregulating PTEN." (PMID 36613528, 2022). "Then, we detected the expression level of serum HCP5 in thyroid, colorectal, and breast cancer, found that its expression in the serum GC was the most specific." (PMID 34222007, 2021). "A great deal of literatures have manifested that HCP5 acts as an important lncRNA during oncogenesis, including osteosarcoma, hepatocellular carcinoma, and breast cancer." (PMID 34187569, 2021). "HCP5 bound to miR-155 at the hub of the ceRNA network of interactions in the basal subtype of breast cancer." (PMID 31137555, 2019). "The results suggested that HCP5 expression was higher in breast cancer patients with TNM III stage (P < 0.001)." (PMID 31215169, 2019). "Then we assessed the expression of HCP5 in human breast cancer tissues, we detected HCP5 mRNA by RNA Scope® 2.0 technology in 30 paired case‐control TMA." (PMID 31215169, 2019). "Herein, HCP5 was found to be markedly upregulated in malignant OC tumor tissues and OC cell lines, a pattern also observed in lung cancer, prostate cancer, and breast cancer." (PMID 38071681, 2024). "Therefore, increased HCP5-132aa protein expression was correlated with a poor prognosis in breast cancer patients." (PMID 36980766, 2023). "Interestingly, HCP5 has been reported as a ceRNA with involvement in the development of lymphoma, oral squamous cell carcinoma, breast cancer, laryngeal squamous cell carcinoma, and prostate cancer." (PMID 34488675, 2021). "Moreover, breast cancer patients with elevated levels of HCP5-132aa had a worse prognosis." (PMID 36980766, 2023). "There were positive correlation between HCP5 and BIRC3 in breast cancer patients (R = 0.625, P < 0.001)." (PMID 31215169, 2019). "To assess the expression of HCP5 in TNBC, we first detected the mRNA level in the human normal breast epithelial cell line MCF‐10A and breast cancer cell lines by qPCR." (PMID 31215169, 2019). "In this sense, from the generated data, we evidence here two lncRNAs, UCA1 and HCP5, which have not yet been identified in the context of the tumoral immune response in breast cancer." (PMID 37835376, 2023). "The results showed that HCP5 expression was not statistically significant not only in thyroid cancer but also in colorectal cancer, and in breast cancer had a little significance." (PMID 34222007, 2021). "Compared with the nontumor breast tissues, the expression of HCP5 was significantly elevated in breast cancer samples." (PMID 31215169, 2019).
breast carcinoma (continued). "To determine whether HCP5-132aa was expressed endogenously, we conducted western blot analysis to detect HCP5-132aa protein expression in normal human mammary epithelial cells MCF-10A and breast cancer cell lines T47D, MCF-7, SKBR3, MDA-MB-231, MDA-MB-468, and HCC-1937 cells." (PMID 36980766, 2023).
cervical cancer (11 papers, 2019 to 2024). A primary or metastatic malignant neoplasm involving the cervix. "Research has demonstrated that the level of LncRNA HLA complex P5 (HCP5) was negatively associated with the survival rate of cervical cancer patients." (PMID 33371778, 2021). "Moreover, HCP5 can encourage the development of cervical cancer by inhibiting microRNA-15a regulating metastasis-associated in colon cancer-1 (MACC1)." (PMID 34222007, 2021). "Above all, HCP5, as an oncogene, can promote proliferation and migration ability of cervical cancer via the regulation of the miR-216a-5p/CDC42 axis." (PMID 35399723, 2022). "Subsequently, we found and verified the effect of the new regulatory mechanism of HCP5 on tumorigenicity of cervical cancer by in vitro and in vivo experiments." (PMID 35399723, 2022). "The results displayed that the overexpression of HCP5 promoted cervical cancer cell proliferation and migration in vitro, and the elevated HCP5 can also promote tumor growth in vivo." (PMID 35399723, 2022). "The data above further revealed that HCP5 regulated the miR-216a-5p/CDC42 axis to enhance cervical cancer cell proliferation." (PMID 35399723, 2022). "The results suggested that the expression levels of HCP5 in 25/31 cervical cancer tissues were higher than that of adjacent cancer." (PMID 35399723, 2022). "In conclusion, our results illuminated that HCP5, an oncogenic lncRNA, is overexpressed in cervical cancer, and it can promote tumorigenicity of cervical cancer cells by upregulating CDC42 expression via miR-216a-5p." (PMID 35399723, 2022). "Our results revealed that miR-216a-5p was up-regulated in cervical cancer cells upon HCP5 knockdown, whereas overexpression of HCP5 resulted in a miR-216a-5p decrease." (PMID 35399723, 2022). "In this study, RT-qPCR and western blot demonstrated that lncRNA HCP5 promoted cervical cancer cell line proliferation and migration by inhibiting the expression of miR-216a-5p and resulting in the upregulation of CDC42." (PMID 35399723, 2022). "To further investigate the regulatory role of HCP5 in the progression of cervical cancer, we constructed HCP5 overexpression and knockdown cell models by lentiviral gene transfection vector for molecular mechanism study." (PMID 35399723, 2022). "The following RT-qPCR and clinical characteristics analysis verified the potential carcinogenic role of HCP5 in cervical cancer." (PMID 35399723, 2022). "HCP5 was highly expressed in most malignant tumors, especially triple-negative breast cancer, cervical cancer, esophageal cancer, and hepatocellular carcinoma." (PMID 35399723, 2022). "Nevertheless, high expression of HCP5 led to poor prognosis in invasive ductal carcinoma and cervical cancer." (PMID 35399723, 2022). "In our study, data of Lnc2Cancer and Lncar has shown that HCP5 was highly expressed in cervical cancer tissues and correlated with poor prognosis, but the potential regulatory mechanism remained unclear." (PMID 35399723, 2022). "Results showed that HCP5 enhanced the proliferation and migration of cervical cancer cells." (PMID 35399723, 2022). "lncRNA HCP5 adjustable MACC1 triggers cervical cancer progression." (PMID 35602292, 2022). "Our data verified that HCP5 could interact with miR-216a-5p to partly decrease its anticancer effect and promote cervical cancer progression." (PMID 35399723, 2022). "However, the role and molecular mechanism of HCP5 in cervical cancer progression remain poorly illuminated and need to be further explored." (PMID 35399723, 2022). "However, the expression and functional role of HCP5 in cervical cancer still need to be further explored." (PMID 35399723, 2022). "Whether miR-216a-5p and CDC42 are involved in HCP5-induced growth and migration in cervical cancer was further investigated." (PMID 35399723, 2022).
cervical cancer (continued). "To further explore whether HCP5 affects the biological behavior of cervical cancer cells by regulating miRNAs, we queried starBase v.2.0, which predicted that miR-216a-5p interacted with HCP5." (PMID 35399723, 2022). "Moreover, lncRNA HCP5 overexpression promoted the progression of cervical cancer via MACC1 overexpression through microRNA-15a adsorption." (PMID 33371778, 2021). "Hence, we hypothesized that HCP5 could compete with miR-216a-5p to upregulate CDC42 expression in cervical cancer." (PMID 35399723, 2022). "Taken together, these findings suggest that HCP5 may play a tumorigenic role in cervical cancer." (PMID 35399723, 2022). "In addition, HCP5 can sponge miR-216a-5p in cervical cancer." (PMID 36248798, 2022). "Therefore, HCP5/miR-216a-5p/CDC42 axis may serve as an essential promising therapeutic target for the clinical treatment of cervical carcinoma." (PMID 35399723, 2022). "In contrast, miRNA-15a knockdown experiments or absorption by HCP5 allowed increased MACC1 expression and the proliferation of cervical cancer cells." (PMID 31137555, 2019). "Furthermore, HCP5 and MACC1 were overexpressed in cervical cancer tissues compared to paracancerous tissue, and the survival rate of patients with cervical cancer was negatively correlated to HCP5 expression and positively correlated to miRNA-15a." (PMID 31137555, 2019).
osteosarcoma (10 papers, 2019 to 2024). A usually aggressive malignant bone-forming mesenchymal neoplasm, predominantly affecting adolescents and young adults. "On the contrary, the in vitro downregulation of HCP5 led to a notable inhibition of proliferation, migration, invasion and enhanced apoptosis in osteosarcoma cell lines." (PMID 35563562, 2022). "In the clinical setting, a high expression of HCP5 in tissue samples retrieved from osteosarcoma patients was significantly correlated to low survival and poor prognosis." (PMID 35563562, 2022). "Knockdown of HCP5 plays an inhibitory effect on osteosarcoma cells proliferation, invasion, and epithelial-mesenchymal transition (EMT)." (PMID 34187569, 2021). "Recently, Zhao and Li showed that transcription factor SP1 induced upregulation of HCP5, which in turn promoted the development of osteosarcoma, whereas inhibition of HCP5 expression reversed cell invasion and epithelial–mesenchymal transition." (PMID 31137555, 2019). "Therefore, the HCP5/miR-101/EPHA7 axis has been correlated to osteosarcoma malignant development, as HCP5 promotes the increased expression of EPHA7 via targeting miR-101 competitively." (PMID 35563562, 2022). "Also, the ubiquitous transcription factor SP1, which is known to regulate MHC class I gene expression both constitutively and in a tissue-specific manner, was shown to upregulate HCP5 expression and induce the development of osteosarcoma." (PMID 31137555, 2019). "Functional tests verified that HCP5 could function as an oncogene in osteosarcoma and was activated by the transcription factor 1 (SP1), convincing that SP1 induced the up-regulation of HCP5, which impacted the development of osteosarcoma." (PMID 34222007, 2021). "Consequently, HCP5, miR-101 and EPHA7 could be further considered as potential prognostic biomarkers and therapeutic targets for osteosarcoma treatment." (PMID 35563562, 2022).
hepatocellular carcinoma (9 papers, 2016 to 2024). A malignant tumor that arises from hepatocytes. "The HCP5 gene was principally expressed in immune system cells, which affects susceptibility to hepatitis C virus-associated hepatocellular carcinoma." (PMID 39279987, 2022). "The MICA/HCP5 region has been linked to NPC susceptibility and HCV-associated hepatocellular carcinoma." (PMID 26730743, 2016). "Recently, the MICA rs2596542 and DEPDC5 rs1012068 variants in Japanese individuals as well as the HCP5 rs2244546 and PNPLA3 rs738409 variants in European individuals have been found associated with hepatocellular carcinoma (HCC)." (PMID 28928439, 2017).
lung carcinoma (9 papers, 2016 to 2024). "HCP5 was associated with tumorigenesis of many cancers such as pancreatic cancer, colorectal cancer, lung cancer and so on." (PMID 35365175, 2022). "This also was consistent with their finding that at least six HCP5 SNPs, including rs3130907, were associated significantly with lung cancer susceptibility along with the novel risk SNP rs114020893 in the lncRNA NEXN-AS1 region at 1p31.1." (PMID 31137555, 2019). "The authors noted that lung cancer risk-related loci (6p21 and 15q25) were enriched in lncRNAs, such as HCP5, RP11-650L12.2, XXbac-BPG27H4.8, and HCG17, and that using noncoding regions in GWAS and gene-based and pathway-based analyses should be complementary to protein coding-related approaches." (PMID 31137555, 2019). "Previously, HCP5 has been reported to promote cell proliferation and metastasis in multiple cancers, such as thyroid cancer, lung cancer, and colorectal cancer." (PMID 32300102, 2020). "This in part confirmed a previous study that found that HCP5 was involved in the process of lung cancer by competing with PDL2, an immune checkpoint gene, and FGL2, a therapeutic target to suppress carcinogenesis." (PMID 31137555, 2019). "It was suggested that HCP5 may involve in the process of lung cancer by competing with PDL2 and FGL2." (PMID 29069717, 2017).
triple-negative breast carcinoma (9 papers, 2019 to 2025). An invasive breast carcinoma which is negative for expression of estrogen receptor (ER), progesterone receptor (PR), and human epidermal growth factor receptor 2 (HER2). "The objective of the study was to investigate the possibility of lncRNA HCP5-encoded peptide/protein and the role of the resulting product in triple-negative breast cancer." (PMID 36980766, 2023). "Our study revealed that lncRNA HCP5 encodes a 132-amino acid sequence, referred to as HCP5-132aa, which enhances the growth of triple-negative breast cancer cells by regulating ferroptosis." (PMID 36980766, 2023). "The current study aims to investigate whether lncRNA HCP5-encoded products promote triple-negative breast cancer (TNBC) by regulating ferroptosis." (PMID 36980766, 2023). "Knocking down HCP5 can regulate miR-219a-5p to inhibit triple-negative breast cancer cell growth and induce apoptosis." (PMID 35602292, 2022). "LncRNA HCP5 was also found to be higher in triple-negative breast cancer tissues and cell lines, and silencing HCP5 led to suppression of cell proliferation and induction of cell apoptosis." (PMID 33371778, 2021). "In triple negative breast cancer, HCP5 as a ceRNA to regulate BIRC3 by sponging miR-219a-5p, thereby promoting cancer progression." (PMID 34923990, 2021). "It has been reported that lncRNA HCP5 is highly expressed in triple-negative breast cancer." (PMID 35602292, 2022). "HCP5 promotes cisplatin resistance by targeting PTEN in triple-negative breast cancer." (PMID 35602292, 2022). "Furthermore, the inhibitory function of si-HCP5 against OC metastasis and growth was verified in a xenograft model established with OC cells, the results of which were in line with the research of HCP5 in nasopharyngeal carcinoma and in triple-negative breast cancer." (PMID 38071681, 2024).